CAV1 (caveolin 1)
Diseases named in the same sentence as CAV1 in open-access papers (continued):
Sharing a sentence is not in itself a finding about the gene and the disease.
lung carcinoma (continued). "Taken together, these results indicate that cordycepin promotes CAV1 upregulation to enhance JNK/Foxo3a signaling pathway activation, inducing apoptosis in lung cancer cells, and support its potential as a therapeutic agent for lung cancer." (PMID 28099944, 2017). "Similarly, P-gp localises in the caveolae of MDR cells where it is colocalised with Cav-1 in many cells including CHRC5 chemoresistant cells, A549 lung carcinoma cells and brain endothelial cells." (PMID 29062386, 2017). "First, we found that CAV1-mediated p-JNK upregulation and the reduction of p-Foxo3a preceded A549 lung cancer cell apoptosis, suggesting that JNK phosphorylation and Foxo3a dephosphorylation were involved in the mediation of cordycepin-induced A549 cell apoptosis." (PMID 28099944, 2017). "To generalize Cav‐1 knockdown‐induced cellular senescence, we repeated this set of experiments in HCT116 human colorectal carcinoma cells, human diploid fibroblasts (HDFs), and H460 human lung cancer cells." (PMID 28514055, 2017). "The migration of H460 large lung cancer cells was inhibited by 100 μM H2O2; the superoxide anion and hydrogen peroxide downregulated Cav-1 expression and inhibited cell migration and invasion, whereas the hydroxyl radical upregulated Cav-1 expression and promoted cell migration and invasion." (PMID 27375834, 2016). "Fourteen negative primary tumors shifted to Cav1 positivity during metastasis, whereas two positive lung carcinomas lost Cav1 expression in the brain metastatic tissue." (PMID 26315660, 2015). "Concerning lung cancer, normal human lung epithelial cultures abundantly express Cav1, whereas its expression is reduced or absent in 95% of small-cell lung cancer cell lines and is retained in 76% of NSCLC cells." (PMID 26315660, 2015). "The tumor-promoting effect of Cav-1 in SWCNT-transformed cells is similar to that observed in human lung cancer cell lines, indicating a potential shared mechanism between laboratory SWCNT-driven tumors and human lung cancer." (PMID 24939878, 2014). "Further support comes from our findings that overall survival in untreated patients with lung cancer does not differ by CAV1 expression status." (PMID 25222296, 2014). "Even though Cav-1 was shown to potentiate lung cancer metastasis by enhancing anoikis resistance and invasion and migration, the present study provided the inhibitory effect of Cav-1 on cancer-endothelium adhesion which has not been demonstrated." (PMID 23460862, 2013). "Immunohistochemistry was also performed to determine the expression and subcellular localization of the cav-1 protein in the 115 paraffin-embedded lung cancer specimens and 19 non-cancerous lung specimens." (PMID 22200856, 2012). "The levels of cav-1 mRNA and protein expression were significantly lower in lung cancers when compared to matched TF or non-cancerous lung tissues." (PMID 22200856, 2012). "Two previous studies showed that the expression of the cav-1 gene was down-regulated in lung cancer cells compared to normal bronchial epithelial cells." (PMID 22200856, 2012). "Additionally, in specific cases a relatively high change in Young’s modulus did not correspond to marked expression changes of a given gene — see for example low CAV1 changes observed in MCF10A PIK3CA mutant, or low IGFBP7 changes in intestine and lung carcinoma samples." (PMID 39960760, 2025). "Also, CAV1 positively regulates the expression and activity of multiple oncogenic factors, including Akt, CCND1, as well as BCL-2, thus protecting cells from apoptotic cell death in lung cancer." (PMID 33435156, 2021). "Cav-1 is mainly a negative predictor for lung cancer outcomes." (PMID 31991790, 2020). "What is more, in both lung cancer patients with smoke history or no, Cav-1 exhibits a positive correlation with better OS, indicating that Cav-1-targeting strategy might be effective for lung cancer patients independent of the factor of smoke." (PMID 28546853, 2017).
lung carcinoma (continued). "The high expression of Cav-1 has been identified in a number of MDR cancer cells, including colchicine-resistant HT-29-MDR cells, vinblastine-resistant SKVLB1 ovarian carcinoma cells, taxol-resistant A549-T24 lung carcinoma cells, and adriamycin-resistant MCF-7 breast adenocarcinoma cells." (PMID 29062386, 2017). "Further, patient survival data also showed reduced progression free survival and poor prognosis of lung cancer patients carrying CAV-1 mutation, and the disease-free survival among those patients was 50 months as compared to more than 179 months for patients without CAV-1 genetic alteration." (PMID 34762666, 2021). "Even though our data show that CAV1 silencing increases taxane- but not platinum sensitivity the possibility exists that intracellular pharmacokinetics of other drugs used in lung cancer therapy such as gemcitabine or etoposide may be dependent on CAV1 mediated mechanisms as well." (PMID 25222296, 2014). "In our 211 primary lung cancer cases, higher Cav-1 expression was seen in the SQC (52%) group than in the non-SQC group (33%), supporting a relationship between Cav-1 expression and lung cancer histology." (PMID 31297035, 2019). "Although many molecules, such as caveolin-1, CRMP-1 and CTGF, have been reported as being important in promoting or inhibiting invasion and metastasis of lung cancer based on the cell line series, this model has not been used in radiation-related studies to date." (PMID 23614048, 2013). "In addition, although CAV1, SMAD7, BMP2, EDN1, and CXCL12 were not significantly different in the prognostic analysis in our study, they also play important roles in the occurrence and development of lung cancer." (PMID 34820377, 2021).
melanoma (110 papers, 2009 to 2025). A malignant, usually aggressive tumor composed of atypical, neoplastic melanocytes. "This dual role aligns with our findings: the loss of CAV1 in RB and spindle/myxoid melanoma suggests a tumor-suppressor role in less aggressive settings, while its gain in epithelioid melanoma points to its pro-metastatic activity." (PMID 41374987, 2025). "In melanoma specifically, CAV1 has been implicated in promoting metastasis in experimental models and is associated with metastatic risk in patients." (PMID 41374987, 2025). "B16F10 melanoma cells were stably transfected with either the empty vector (pLacIOP) or the plasmid with a CAV1-encoding insert (pLacIOP-CAV1)." (PMID 38069269, 2023). "Loss of CAV1 in tumor stroma confers poor outcomes in prostate, breast, ovarian, esophageal, gastric, liver, and pancreatic cancers and melanoma." (PMID 35158857, 2022). "Previous studies showed the associations of high expression of CAV1 in CAFs with cancer progression and a poor prognosis in patients with pancreatic cancer, kidney carcinoma, colon carcinoma, and melanoma." (PMID 35045883, 2022). "Although increased expression of CAV1 in tumor cells is thought to be associated with aggressiveness and poor survival, the correlation between CAV1 expression and melanoma remains largely unexplored." (PMID 36431795, 2022). "Melanoma cells express channel isoforms belonging to the Cav1 (which mainly encodes high-voltage-activated L-type channels) and Cav2 (which encodes high-voltage-activated P⁄ Q-type, N-type, and R-type channels) gene families." (PMID 34575835, 2021). "For instance, plasma exosomes bearing CD63, a classic exosome marker, and Cav1—which is elevated in prostate cancer and melanoma —are useful melanoma markers and are associated with poor prognosis in melanoma." (PMID 34496872, 2021). "Taken together, these findings suggest that mutation of the S80 residue affected the ability of CAV1 to suppress tumor growth of B16F10 melanoma cells, associated with a loss in the capacity of CAV1 to repress UPR signaling." (PMID 32811828, 2020). "In fact, in lymph node metastases of malignant melanoma loss of stromal caveolin 1 (Cav-1) expression, that is a marker of autophagy, glycolysis, and oxidative stress, strongly predicts clinical outcome." (PMID 32528879, 2020). "For melanoma, increased CAV1 expression was associated with disease progression by favoring migration, invasion and metastasis." (PMID 31362353, 2019). "For melanoma (sdis = − 0.16; p = 1.0e−3; and = 5.2e−6) E-Cadherin, Caveolin-1, and c-Kit expression levels are decreased for mutated cases, and MAPK_pT202_Y204 is increased." (PMID 30442178, 2018). "CAV1 up-regulation has been linked to an increase in the migration of breast, colon, melanoma and endometrial cancer cells." (PMID 29340103, 2017). "Previous studies linked Cav1 overexpression with melanoma malignancy showing that its secreted amounts loaded in the exosomal cargo were involved in cell migration." (PMID 26912358, 2016). "In summary, these experiments provide compelling evidence that CAV1 increases important migration-associated parameters of metastatic melanoma cells in an ECM-dependent fashion." (PMID 27259249, 2016). "More recently, exosomes containing CAV1 were detected in the serum of melanoma patients and associated with a poor prognosis because of their immune suppressive effects." (PMID 24500501, 2014). "Under these experimental circumstances, CAV1 presence was identified as a postsurgery risk factor because expression in B16F10 melanomas favoured metastasis to the lung after intervention." (PMID 24500501, 2014). "In summary, enhanced CAV1 expression in human melanomas is linked here to augmented metastatic potential." (PMID 24500501, 2014). "Caveolin-1 expression in melanoma is associated with increased cellular proliferation, and in some studies, enhanced tumour cell invasion and migration." (PMID 22127285, 2012).
melanoma (continued). "Thus, if a decrease in melanoma aggressiveness and metastasis development is associated with a decrease in CAV1 expression, a higher extract concentration is required." (PMID 36431795, 2022). "However, cycloheximide chase experiment confirms that leptin and resistin cause the stabilization of FASN and Cav-1 protein levels respectively in melanoma cells." (PMID 29568521, 2018). "Very recently, it has been shown that genetic ablation of Cav1 differentially affects melanoma tumour growth and metastasis in mice, as Cav1-deficient dermal fibroblasts are able to promote the growth of melanoma cells via enhanced paracrine cytokine signalling." (PMID 23521716, 2013). "As a consequence, Cav1 plasma levels could bear relevance as a possible prognostic marker in melanoma patients, and exosomes may represent a hallmark of more aggressive melanoma that identifies patients with poor outcome." (PMID 23521716, 2013). "Considering our previous study on HFD mice, normalized serum levels of these adipokines, via reduced adiposity, could be associated with a reduction in FASN and Cav-1 protein levels and decrease in Akt activation, leading to reduced progression of melanoma in the experimental HFD mice." (PMID 29568521, 2018). "Mixoid melanoma also displayed reduced CAV1, with patchy, weakly positive fluorescent areas scattered irregularly throughout the tumor mass." (PMID 41374987, 2025). "Cav1 expression is notably elevated in melanoma cell lines, and its silencing has been shown to reduce tumor growth and angiogenesis." (PMID 40963741, 2025). "In melanoma, EVs purified from human plasma samples revealed significantly high levels of Cav1/Rab-5b double-positive EVs in patients compared to healthy donors, underscoring its potential as a disease biomarker." (PMID 40963741, 2025). "Caveolin-1 demonstrates context-dependent roles, acting as a tumor suppressor in RB and less aggressive melanomas, but supporting invasive features in epithelioid melanoma." (PMID 41374987, 2025). "In melanoma cells, acidic microenvironments increase EV release from donor cells and facilitates Cav1 delivery to recipient cells." (PMID 40963741, 2025). "In melanoma cells, Cav-1 interacts with FASN, and elevated levels of both Cav-1 and FASN, along with phosphorylated Akt, promote cell proliferation." (PMID 38921444, 2024). "Diet-induced obesity exacerbates melanoma progression in male C57BL/6J mice, which is associated with the elevated expression of Caveolin-1 (Cav-1) and FASN in tumors from mice on a high-fat diet." (PMID 38921444, 2024). "CAV1 expression augmented migration, invasion, and metastasis of melanoma cells, and these effects were abolished via transient co-expression of E-cadherin." (PMID 38069269, 2023). "We also corroborated these observations using the human melanoma line A375, which has elevated basal expression levels of CAV1 in comparison to B16F10 cells." (PMID 38069269, 2023). "We previously showed that the increased expression of CAV1 in A375 human melanoma cells, A375 (CAV1), treated for 48 h with IPTG, increased migration, invasion, and metastasis in comparison with A375 (mock) cells." (PMID 38069269, 2023). "A diminished level of caveolin-1 expression has also been shown in stromal cells across several types of cancers, such as prostate, gastric, and melanoma." (PMID 38067108, 2023). "Conversely, increased caveolin-1 expression has been seen in melanoma cell lines, where caveolin-1 Y14 phosphorylation plays a role in promoting tumor progression, or in Ewing’s sarcoma, where its increased expression triggers MMPs-induced metastatic invasion." (PMID 38067108, 2023). "Compared with ABCB5, the role of CAV1 in skin diseases is more complex, as expression depends on the type of melanoma." (PMID 36431795, 2022). "For a more substantiated explanation, it is necessary to investigate the relationship of CAV1 with the aggressiveness of melanoma and the development of metastases in more detail in the future." (PMID 36431795, 2022).
melanoma (continued). "CAV1 expression has been shown to stimulate the proliferation of B16F10 melanoma cells while inhibiting migration and invasion in vitro." (PMID 36431795, 2022). "The same group reported that CAV1-enhanced melanoma cell migration, invasion, and metastasis in vivo via tyrosine-14 phosphorylation of CAV-1 by Src family kinases." (PMID 36532050, 2022). "Extracellular vesicles containing Cav-1 are related to tumor development and progression; in addition, cav-1 levels increase in exosomes from melanoma serum as compared to exosomes from healthy individuals." (PMID 36015073, 2022). "In contrast, some studies have reported that CAV-1 expression enhances metastasis in murine and human melanoma cell lines along with reduced E-cadherin and Rac-1 activation." (PMID 36532050, 2022). "Under the conditions of the extracellular matrix integrin interaction and Tyr-14 phosphorylation, CAV1-enhanced melanoma cells will migrate, invade, and migrate to the lungs." (PMID 36110205, 2022). "Specifically, results from our own group showed that PTP1B controls the migration of melanoma cells by dephosphorylating CAV1 tyrosine-14." (PMID 35740528, 2022). "The co-injection of Cav1-deficient dermal fibroblasts with melanoma cells is sufficient to recapitulate the tumor phenotype observed in Cav1-null mice as the Cav1-null fibroblasts promoted the growth of melanoma cells via enhanced paracrine cytokine signaling." (PMID 35158857, 2022). "While a higher amount of CD63-positive and caveolin-1-positive exosomes were found in melanoma patients, detection based on caveolin-1-positive exosomes was more sensitive than that targeting CD63." (PMID 34575876, 2021). "In melanoma, for example, the genetic mutation of PTEN increases Cav-1-mediated dissociation of β-catenin from membranous E-cadherin bypassing senescence process and promoting metastasis." (PMID 34490102, 2021). "For example, the presence of CAV-1 in EVs from breast metastatic cells is associated with enhanced migration and invasion of recipient cells and the EV transfer of MET with melanoma metastasis to the bone marrow." (PMID 33114492, 2020). "T-EVs from the plasma of melanoma patients are enriched in caveolin-1 compared with healthy controls, suggesting that caveolin-1(+) T-EVs are likely to be another prospective melanoma biomarker." (PMID 33081785, 2020). "Previous studies from our laboratory in murine melanoma, metastatic breast, and colon cancer cells showed that the expression of CAV1 favors cell migration in 2D." (PMID 32152405, 2020). "This study identifies CAV1 as a novel substrate for PTPN14, since the phosphatase co-immunoprecipitates with CAV1 in murine melanoma cells B16F10 that express E-cadherin and over expression of PTPN14 reduces the phosphorylation of CAV1 on Y14." (PMID 32152405, 2020). "Using cell culture and in vivo models of melanoma, we provide evidence indicating that the expression of CAV1 strongly represses the ability of cancer cells to engage the UPR, ablating an adaptive capacity to cope with ER stress." (PMID 32811828, 2020). "In melanoma cells, CAV1 expression suppresses tumor formation, but the protein is largely absent from the plasma membrane and does not form caveolae." (PMID 32811828, 2020). "In this sense, CAV1 increases migration of melanoma metastatic cells, but the co-expression of CAV1 and E-cadherin inhibits tumor formation and lung metastasis." (PMID 32458269, 2020). "Here we report that the tumor suppressor activity of CAV1 is associated with a modulation of the activation of the UPR as shown in cell culture paradigms of ER stress and melanoma models in vivo." (PMID 32811828, 2020). "With this approach, it has been shown that CD63+ and CAV1+ plasma exosomes levels were significantly higher in melanoma patients as compared to healthy donors." (PMID 32916840, 2020).